KCNH3 (potassium voltage-gated channel subfamily H member 3)
Description:
Pore-forming (alpha) subunit of a voltage-gated inwardly rectifying potassium channel. Charactherized by a fast rate of activation during depolarization followed by a rapid inactivation at much more depolarized value causing inward rectification due to a C-type inactivation mechanism. Exhibits a rapid recovery from inactivation.
Synonyms: BEC1; ELK2; Kv12.2
Tractability: Small molecule: an approved drug acts on it; a high-quality ligand is known; it belongs to a druggable protein family. Antibody: its Gene Ontology location is reachable by antibodies, with high confidence; UniProt places it where antibodies can reach, with medium confidence; UniProt predicts a signal peptide or a membrane-spanning region. PROTAC: a small molecule that binds it is known.
Target class: Potassium channels; Ion channel; Voltage-gated ion channel; Voltage-gated potassium channel
Gene: Protein-coding gene on chromosome 12 (49,539,028 to 49,558,337, forward strand). Ensembl gene ENSG00000135519.
Subcellular location: Cell membrane
Pathways (Reactome):
Neuronal System: Voltage gated Potassium channels
Gene Ontology:
Molecular function: inward rectifier potassium channel activity; protein binding; voltage-gated potassium channel activity; monoatomic ion channel activity
Biological process: potassium ion transport; potassium ion transmembrane transport; regulation of membrane potential; monoatomic ion transport; transmembrane transport
Cellular component: membrane; plasma membrane
Genetic constraint (gnomAD): Loss-of-function variants: 36 observed, 91.67 expected, observed/expected ratio (o/e) 0.39, 90% interval 0.3 to 0.52. The upper end of that interval is the gene's LOEUF score, 0.52, which puts it in group 2 of 6, group 1 being the genes least tolerant of losing a copy. Missense variants: 1,026 observed, 1,454.6 expected, observed/expected ratio (o/e) 0.71, 90% interval 0.67 to 0.74. Synonymous variants: 617 observed, 638.6 expected, observed/expected ratio (o/e) 0.97, 90% interval 0.9 to 1.03.
Homologues: Orthologues: chimpanzee KCNH3 (99% identical), macaque KCNH3 (99% identical), mouse Kcnh3 (96% identical), guinea pig KCNH3 (96% identical), rat Kcnh3 (96% identical), pig KCNH3 (95% identical), dog KCNH3 (95% identical), rabbit KCNH3 (93% identical), tropical clawed frog kcnh3 (54% identical), Drosophila melanogaster Elk (40% identical), zebrafish kcnh6a (31% identical), Caenorhabditis elegans unc-103 (23% identical), and 12 more. Paralogues in human: KCNH8 (49% identical), KCNH4 (46% identical), KCNH2 (32% identical), KCNH7 (30% identical), KCNH6 (29% identical), KCNH1 (28% identical), KCNH5 (28% identical), HCN4 (16% identical), HCN1 (15% identical), HCN2 (15% identical), CNGA3 (14% identical), HCN3 (13% identical), and 5 more.
Diseases named in the same sentence as KCNH3 in open-access papers:
KCNH3 is named in the same sentence as 10 diseases in open-access papers, as found by Europe PMC text mining. Sharing a sentence is not in itself a finding about the gene and the disease. The quoted sentences say what the papers report.
epilepsy (3 papers, 2013 to 2025). A brain disorder characterized by episodes of abnormally increased neuronal discharge resulting in transient episodes of sensory or motor neurological dysfunction, or psychic dysfunction. "Although mutations in the Elk subfamily have not been previously associated with PMEs or epilepsy, genetic deletion and drug inhibition of KCNH3 in a mouse model demonstrated hippocampal hyperexcitability and epilepsy with brief myoclonic activity." (PMID 39156922, 2024). "The FS-DE network has three distinctive VIPs, CACNG2, KCNH3 and GNG3, with relevant roles in epilepsy." (PMID 24278214, 2013).
cognitive deficits (1 paper, 2018). "KCNH3 is concentrated in the forebrain, and its overexpression in mice leads to cognitive deficits." (PMID 30462746, 2018).
developmental delay (1 paper, 2023). "In patient NJ233 who presented with global developmental delay, microcephaly, growth retardation and slightly dysmorphic features was found to have compound heterozygous variants (NM_012284: c.961C > T;p.His321Tyr/c.2812_2813del;p.Leu938ValfsTer73) in KCNH3." (PMID 37501076, 2023).
schizophrenia (1 paper, 2019). A major psychotic disorder characterized by abnormalities in the perception or expression of reality. "A growing body of evidence implicates several calcium and potassium channels in the susceptibility of schizophrenia, such as CACNA1C (Cav1.2 α subunit), KCNN3 (SK3), KCNH3 (Ether-A-Go-Go), and KCNJ3 (Kir3.1)." (PMID 31920555, 2019).
KCNH3 also shares sentences with these, for which no sentence is quoted: attention deficit-hyperactivity disorder (1 paper); autism spectrum disorder (1); genetic disorder (1); microcephaly (1); mucolipidosis type IV (1); neurodevelopmental disorder (1).